E2F3 (E2F transcription factor 3)
Diseases named in the same sentence as E2F3 in open-access papers (continued):
Sharing a sentence is not in itself a finding about the gene and the disease.
lung adenocarcinoma (17 papers, 2012 to 2025). A carcinoma that arises from the lung and is characterized by the presence of malignant glandular epithelial cells. "The expression of this miRNA has been related to the inhibition of E2F3 and the progression of lung adenocarcinoma." (PMID 40089674, 2025). "The low expression of miR-200b is reported to induce E2F transcription factor 3 overexpression and increase the chemoresistance of patients with lung adenocarcinoma to docetaxel." (PMID 30717818, 2019). "In lung adenocarcinoma, overexpression of miR-432 inhibited cell proliferation through arresting cell cycle by regulation of two directly targets E2F3 and AXL." (PMID 28947999, 2017). "It was also reported that miR-200b reverses chemoresistance of docetaxel-resistant lung adenocarcinoma cells by targeting E2F3 through G2/M phase." (PMID 29156719, 2017). "Our previous study have shown that enforcement of miR-200b reversed docetaxel chemoresistance of lung adenocarcinoma cells by inducing G2/M cell cycle arrest through targeting E2F3." (PMID 28947999, 2017). "Our previous study identified miR-200b/E2F3 axis as a chemosensitivity restorer of human lung adenocarcinoma (LAD) cells." (PMID 27027446, 2016). "In our previous study, E2F3 is also found to be a direct target of miR-200b, and inhibition of miR-200b, which led to E2F3 overexpression, contributed to resistance of lung adenocarcinoma cells to docetaxel." (PMID 24106980, 2013). "Bhattacharjee showed another mRNA expression factor with increased expression; that is, E2F3 has a fold change of 3.002 in patients with lung adenocarcinoma and a fold change of 3.002 in patients with SCLC compared with that in patients with normal lung tissues." (PMID 29754146, 2018). "Our previous results showed for the first time that miR-200b could be used as a restorer of chemosensitivity of lung adenocarcinoma cells to docetaxel, mediated at least partially by targeting E2F3." (PMID 28947999, 2017). "Similarly, in lung adenocarcinoma, miR-432 functioned as a tumor suppressor gene through targeting E2F3 and AXL." (PMID 28947999, 2017). "Moreover, miR-200b interplayed with E2F3, contributing to the decrease in the chemical sensitivity of lung adenocarcinoma cells to docetaxel." (PMID 28903320, 2017). "Previously, we also showed that re-expression of miR-200b could reverse docetaxel chemoresistance of lung adenocarcinoma cells through growth inhibition by targeting E2F3." (PMID 28947999, 2017). "Previously, we showed that miR-200b, which was identified as the most down-regulated miRNA in docetaxel-resistant SPC-A1/DTX cells, could promote docetaxel resistance in lung adenocarcinoma cells by directly targeting E2F3." (PMID 28947999, 2017). "In a recent research, tissue inhibitor of metalloproteinases-1 (TIMP-1) was reported to lead to a pro-tumourigenic increase of miR-210 in lung adenocarcinoma cells along with their exosomes and E2F3, a downstream target of miR-210, was decreased in the presence of TIMP-1." (PMID 28947999, 2017). "E2F3 is overexpressed in 55–70% squamous cell carcinomas and 79% of adenocarcinomas of the lung." (PMID 22242187, 2012). "E2F transcription factor 3 (E2F3) and ZEB1 are targets of miR-200b and regulated docetaxel resistance in lung adenocarcinoma cells." (PMID 35682560, 2022). "In cytoplasm, MALAT1 weakens the binding of miR-200b to E2F transcription factor 3(E2F3) and ZEB1 mRNAs, thus leading to increase of E2F3 and ZEB1 protein expression and chemoresistance of lung adenocarcinoma cells." (PMID 34976181, 2022). "The results indicated that the expression levels of E2F1, E2F2, E2F3, E2F5, E2F6, E2F7, and E2F8 were higher in lung adenocarcinoma and squamous cell lung carcinoma tissues than in lung tissues, whereas and the expression level of E2F4 was lower in the former than in the latter." (PMID 29754146, 2018).
lung adenocarcinoma (continued). "They reported that the expression of miR-200b ectopically reversed docetaxel-induced chemoresistance of lung adenocarcinoma cells; furthermore, luciferase reporter assays containing a 3′ UTR sequence of E2F3 mRNA showed that miR-200b could directly target E2F3." (PMID 38413011, 2024).
colon cancer (16 papers, 2014 to 2023). "Our findings disclosed that the expression of E2F3 had an association with colon cancer stage, meanwhile the expression of E2F7 in colon cancer tissues were significantly increased in patients with colon cancer." (PMID 32117628, 2020). "In line with this, MEX3A upstream regulator E2F3 also functions as an oncogenic transcription factor in a variety of cancers 41-43, and high E2F3 levels confer poor overall survival and disease-free survival in patients with colon cancer." (PMID 36276637, 2022). "Analogous to Mex3a, E2f3 is also dramatically upregulated in AOM-DSS-induced mouse colon tumors, and is highly expressed in ISCs and in regenerative foci following irradiation." (PMID 36276637, 2022). "The Kaplan-Meier Plotter showed that the high levels of E2F3 conferred a worse overall survival and disease free survival of patients with colon cancer." (PMID 32117628, 2020). "In colon cancer, E2F3 serves as a direct target of miR-503 that is responsible for the proliferation and cell cycle distribution." (PMID 32117628, 2020). "In our report, the expression of E2F3 in colon cancer tissues was higher than that in normal tissues." (PMID 32117628, 2020). "Previous studies have shown that mir-129 suppresses expression of BCL2, TS, and E2F3 in colon cancer." (PMID 29507661, 2018). "Gene α1-integrin (ITGA1) and transcription factor E2F3 have been found related to the prevention of tumor progression in colon cancer patients." (PMID 30397551, 2018). "We further revealed this impact on colon cancer stem cells was due to the inhibition of E2F3, and BCL2 by Western immunoblot analysis." (PMID 29507661, 2018). "MiR-34a was previously reported to induce senescence-like growth arrest through modulation of the E2F1/E2F3 expression in human colon cancer cells and leukemic cells." (PMID 28389657, 2017). "miR-449b inhibited the cell growth and viability of SW1116 colon cancer stem cells via reduction of E2F3." (PMID 28947999, 2017). "MiR-449b was found to play a tumor-suppressive role by down-regulating E2F3 expression and reducing the proliferative ability of colon cancer stem cells." (PMID 25889255, 2015). "The results showed that lower level of E2F3 may contribute to better disease free survival in patients with colon cancer." (PMID 32117628, 2020). "Additionally, E2F3, E2F4, E2F7 and E2F8 were significantly associated with the stages of colon cancer." (PMID 32117628, 2020). "Importantly, an aberrant functional network comprising miR-34a/Sirt1/E2F3 was testified to promote the proliferation of the 5-FU-resistant colon cancer cells." (PMID 28947999, 2017). "Other findings indicated that EGFR signals could coordinately control multiple G1 regulators via miR-143 and its target K-ras and miR-145 and its targets MYC, cdk6, CCND2 or E2F3, which play a role in cell cycle progression in colon cancer." (PMID 28947999, 2017). "In colon cancer, transfection of miR-449b precursor could significantly increase the number of cells in the G0-G1 phase via regulation of cell cycle function of E2F3." (PMID 28947999, 2017). "We focused on E2F3 because CDK6 has been reported as a target of miR-145 in colon cancer." (PMID 25762621, 2015). "Finally, it was revealed that E2F3 affected the STAT3 pathway to modulate stemness in colon cancer." (PMID 37456248, 2023). "Moreover, E2F3 facilitated colon cancer cell migration and invasion." (PMID 37456248, 2023). "In addition, the expression of E2F3, E2F4, E2F7 and E2F8 were significantly associated with tumor stages and overall survival of the patients with colon cancer, suggesting that they may serve as potential therapeutic targets for colon cancer." (PMID 32117628, 2020). "Additionally, dysregulation of miR-449b/E2F3 signal plays a role in the self-renewal and proliferation of colon cancer stem cell and targeting this signal will be a potential strategy for the treatment of colon cancer." (PMID 28947999, 2017).
colon cancer (continued). "Hsa-mir-377 targets ETS1 to inhibit human clear cell renal cell carcinoma 38, targets E2F3 to inhibit non-small cell lung cancer 39, and targets BRD4 to inhibit colon cancer." (PMID 36741263, 2023). "The inhibition of E2F3 not only suppressed proliferation but also triggered apoptosis and G0/G1 arrest in SW480 colon cancer cells." (PMID 32117628, 2020). "Our study implied that E2F3, E2F4, E2F7 and E2F8 are potential targets of precision therapy for patients with colon cancer while E2F1, E2F2, E3F3, E2F5, E2F7 and E2F8 are potential biomarkers for the diagnosis of colon cancer." (PMID 32117628, 2020). "The Kaplan–Meier showed that E2F3 and E2F4 displayed significantly correlation with the overall survival of patients with colon cancer." (PMID 32117628, 2020). "In murine models of colon cancer, miR-143 and miR-145 played tumor suppressive functions by targeting Cdk6, CCND2 and E2F3." (PMID 28947999, 2017). "Another study found miR-449b acts as a tumor suppressor in colon cancer stem cells through CCND1 and E2F3 down-regulation." (PMID 28821833, 2017). "The top oncogenic signatures identified from male smoking include tumor suppressor genes (PTEN and RB1), colon cancer gene sets (CTIP and SNF5), skin tumor progression protein (ATF2), oncogenic signatures KRAS-600-LUNG and E2F3 pathway genes." (PMID 25621181, 2014). "The results demonstrated that the expression levels of E2F3, E2F4, E2F7 and E2F8 displayed significant correlation with the tumor stage in patients with colon cancer while other members in E2F family in normal group and tumor group did not significantly differ." (PMID 32117628, 2020). "Our studies indicated that the deregulation of E2F1, E2F2, E2F3, E2F5, E2F7 and E2F8 in colon cancer tissues might play a vital role in colon cancer oncogenesis, which could be promising diagnostic biomarkers for LUAD." (PMID 32117628, 2020).
non-small cell lung carcinoma (15 papers, 2014 to 2023). A group of at least three distinct histological types of lung cancer, including non-small cell squamous cell carcinoma, adenocarcinoma, and large cell carcinoma. "A rencent study showed that the long non-coding RNA, NEAT1, promotes non-small cell lung cancer progression via regulation of the miR-377/E2F3 pathway." (PMID 29050301, 2017). "For instance, NETA1 functioned as a ceRNA for miR-377-3p, antagonized its function, and led to the derepression of its endogenous target E2F3, which was a core oncogene in promoting non-small-cell lung carcinoma progression." (PMID 29147064, 2017). "E2F1, E2F2, and E2F3 are up-regulated in non-small cell lung cancer." (PMID 29254182, 2017). "In addition, NEAT1 enhances non-small cell lung cancer (NSCLC) via regulation of miR-377-3p-E2F3 pathway." (PMID 27926523, 2017). "Knock-down of E2F1 and E2F3 inhibited migration and invasion of non-small cell lung cancer cells." (PMID 25568667, 2014). "Six transcription factors (E2F3, FHL2, ETS1, KAT6B, TWIST1, and RUNX2) were identified in the GRN as essential regulators of gene expression in non-small-cell lung cancer (NSCLC) and related to the lung tumoral process." (PMID 36551878, 2022). "NEAT1 was found to the cell proliferation of non-small-cell lung cancer (NSCLC) though binding hsa-miR-377 and increased the expression of its target E2F3." (PMID 29654165, 2018). "The genes included the pathway non-small cell lung cancer were E2F2, E2F3, TGFA, PRKCG, CDK6, EGF, and CDK4, which were all expressed at significantly higher levels in LUSC tissues in comparison to that in the non-cancer group." (PMID 29394946, 2018).
endometrial cancer (14 papers, 2014 to 2025). Primary or metastatic malignant neoplasm involving the endometrium (mucous membrane that lines the endometrial cavity). "In endometrial cancer, miR-152 inhibited tumor cell growth via targeting novel candidate targets E2F transcription factor 3 (E2F3), tyrosine kinase receptor (MET), and rapamycin-insensitive companion of mTOR (Rictor)." (PMID 34680020, 2021). "E2F3 is a direct downstream target of HOXB9 and is overexpressed in endometrial carcinoma tissues, and E2F3 overexpression enhances endometrial carcinoma cell migration ability." (PMID 34657558, 2021). "To further clarify the expression of E2F3 in EC, we analyzed its expression in a series of 88 endometrial carcinoma using immunohistochemical staining." (PMID 29724991, 2018). "According to a recent report, it was shown that overexpression of miR-34c significantly inhibited proliferation of endometrial carcinoma cells by reducing E2F3." (PMID 28947999, 2017). "In endometrial cancer, the knocking down E2F3 could inhibit the ability of HOXB9 in promoting migration of tumor cell." (PMID 40070576, 2025). "In addition, IGF2BP3 can also promote the proliferation, migration, and invasion of cancer cells in human endometrial carcinoma by enhancing the stability and inhibiting the attenuation of E2F3(E2F transcription factor 3) mRNA." (PMID 38343637, 2024). "Meanwhile, we analyzed the correlation of HOXB9 and E2F3 expression in 88 endometrial carcinoma." (PMID 29724991, 2018). "For instance, in endometrial carcinoma, IGF2BP3 interacts with lncRNA LINC00958 to stabilize E2F3 mRNA, driving tumor progression." (PMID 40313617, 2025). "In endometrial carcinoma (EC), miR-34c was significantly reduced and E2F3 was reduced after up-regulation of miR-34c in the HEC-1-B cell, suggesting that miR-34c functions via reduction of E2F3 protein." (PMID 28947999, 2017).
colorectal cancer (13 papers, 2015 to 2025). A primary or metastatic malignant neoplasm that affects the colon or rectum. "Furthermore, high levels of E2F3 expression are associated with reduced overall survival and disease-free survival rates in colorectal cancer patients, showing significant correlation with cancer staging." (PMID 39045407, 2024). "In colorectal cancer, E2F3 acts as a promoter-regulated factor, exacerbating tumor occurrence during colorectal cancer progression through the STAT3 pathway." (PMID 39045407, 2024). "Supporting the role of MEX3A in radioresistance of colorectal cancer cells, it has been reported that the upstream regulator E2F3 functions on DNA damage response." (PMID 36276637, 2022). "There is a positive correlation with the expression of E2F3 in colorectal carcinoma." (PMID 34820188, 2021). "Moreover, co-expression of SNHG1 with either p70S6k or E2F3 was analyzed through querying open database ChIPBase v2.0 in TCGA colorectal cancer datasets." (PMID 29416759, 2018). "Overexpression of miR-145 resulted in downregulation of p70S6k and E2F3 in colorectal cancer cells." (PMID 29416759, 2018). "Another emerging molecule that might directly affect E2F3 expression is the tumor-suppressor micro RNA miR-448, which has been shown to downregulate E2F3 in colorectal cancer cell lines, inhibiting cell proliferation and inducing apoptosis in this experimental setting." (PMID 36982482, 2023). "Among them, three TF genes, E2F1, E2F3, and BRCA1, were validated as differentially expressed in databases of psoriasis and colorectal cancer, confirming their designation as hub TFs." (PMID 39045407, 2024). "The results showed that SNHG1 was positively correlated with target genes of miR-145 in colorectal cancers (SNHG1 and p70S6k: r: 0.353, p= 3.57E -11; E2F3: r: 0.582, p= 1.86E -31)." (PMID 29416759, 2018). "On chromosomal location Xq26.3, miR-503 was an intragenic miRNA clustered with miR-424, which was significantly decreased in HCC and colorectal cancer (CRC) and functioned as a tumor suppressor by directly targeting E2F3." (PMID 28947999, 2017). "The loss of exosomal miR-200b-3p release from CAFs under hypoxic conditions potentially contributes to colorectal cancer progression by increasing the stemness potential of colorectal cancer cells via upregulation of CD133, SOX2, N-cadherin, ZEB1 and E2F3, which are direct targets of miR-200b-3p." (PMID 39928285, 2025). "Consistently, our recent study demonstrated that compared with E2F1 and E2F3, E2F2 might specifically play a pivotal role in colorectal cancer and serve as a specific therapeutic target." (PMID 35844795, 2022). "Interestingly, miR-34a can negatively regulate 5-FU resistance in human colorectal cancer DLD-1 cells by targeting the SIRT1 and E2F3 genes." (PMID 25585539, 2015). "Also, miR-34a in 5-FU-resistant colorectal cancer (CRC) cells was found to be significantly under-expressed compared with the parental cells after 5-FU treatment and restoration of miR-34a reversed the 5-FU resistance by down-regulation of Sirt1 and E2F3." (PMID 28947999, 2017).
osteosarcoma (12 papers, 2012 to 2022). A usually aggressive malignant bone-forming mesenchymal neoplasm, predominantly affecting adolescents and young adults. "E2F3 (6p22.3) is gained or amplified in approximately 60% of osteosarcomas and encodes the E2F3 transcription factor." (PMID 22685381, 2012). "And hsa_circ_0008934 was found promoted the proliferation and migration of osteosarcoma cells through hsa_circ_0008934 − miR-145-5p − E2F3 axis." (PMID 33722210, 2021). "Overexpression of miR-874 was reported to remarkably inhibit proliferation and metastasis of osteosarcoma by targeting E2F3." (PMID 28947999, 2017). "And, miR-874 inhibited osteosarcoma cell growth by inducing cell apoptosis through downregulation of E2F3." (PMID 28947999, 2017). "For example, miR-145-5p was reported to directly downregulate the expression of E2F3 by seed-matching the 3′-untranslated region (UTR) of E2F3 in osteosarcoma cells, and cell growth was inhibited and G0/G1 arrest occurred when E2F3 was suppressed by miR-145-5p." (PMID 34681596, 2021). "E2F3 was also identified as a target of miR-874 in osteosarcoma cells and E2F3 overexpression could partially reverse its tumor-suppressive effects." (PMID 28947999, 2017). "miR-29 could affect expression of E2F3 and lead to the cell cycle arrest in osteosarcoma." (PMID 28947999, 2017). "Also, re-expression of miR-874 could remarkably suppress migration and invasion of osteosarcoma cells by targeting E2F3." (PMID 28947999, 2017). "In human osteosarcoma cell lines, it was shown that RAD18 is a transcriptional target for the transcription factor E2F3." (PMID 35365623, 2022). "It has been demonstrated that miR-29a, miR-29b and miR-874 were downregulated in most of the osteosarcoma tissues and higher expression of miR-29a increased the expression of E2F1 and E2F3." (PMID 28947999, 2017). "We tested compensation by other activator E2Fs and found that knocking down E2F1 alongside E2F3, but not E2F2, reduced UHRF1 expression in osteosarcoma." (PMID 36068209, 2022).